LINGO3 (leucine rich repeat and Ig domain containing 3)
Synonyms: LERN2; LRRN6B
Tractability: Antibody: UniProt predicts a signal peptide or a membrane-spanning region; its Gene Ontology location is reachable by antibodies, with medium confidence.
Gene: Protein-coding gene on chromosome 19 (2,287,164 to 2,308,174, reverse strand). Ensembl gene ENSG00000220008.
Subcellular location: Membrane
Subcellular location (Human Protein Atlas): Mitochondria
Gene Ontology:
Molecular function: signaling receptor activity
Cellular component: plasma membrane; membrane
Genetic constraint (gnomAD): Loss-of-function variants: 0 observed, 0.58 expected, observed/expected ratio (o/e) 0, 90% interval 0 to 1.82. That is too few expected variants to judge how well the gene tolerates losing a copy. Missense variants: 750 observed, 782.08 expected, observed/expected ratio (o/e) 0.96, 90% interval 0.9 to 1.02. Synonymous variants: 427 observed, 391.5 expected, observed/expected ratio (o/e) 1.09, 90% interval 1.01 to 1.18.
Homologues: Orthologues: chimpanzee LINGO3 (99% identical), macaque LINGO3 (99% identical), pig LINGO3 (94% identical), guinea pig LINGO3 (92% identical), mouse Lingo3 (89% identical), rat Lingo3 (89% identical), dog LINGO3 (83% identical), tropical clawed frog lingo3 (67% identical), zebrafish lingo3a (64% identical), Drosophila melanogaster CG5819 (19% identical), zebrafish lrtm2b (16% identical), Drosophila melanogaster CG4781 (16% identical), and 4 more. Paralogues in human: LINGO4 (43% identical), ECM2 (14% identical), FMOD (14% identical), OGN (13% identical), PRELP (13% identical), EPYC (13% identical), KERA (12% identical), LUM (12% identical), OMD (12% identical), OMG (11% identical).
Diseases named in the same sentence as LINGO3 in open-access papers:
LINGO3 is named in the same sentence as 5 diseases in open-access papers, as found by Europe PMC text mining. Sharing a sentence is not in itself a finding about the gene and the disease. The quoted sentences say what the papers report.
depression (3 papers, 2022 to 2023). "Epigenetic changes in LINGO3 have been correlated with depression and a paralog to LINGO3, LINGO1, acts as a negative regulator of a number of processes key to cognitive function." (PMID 36855151, 2023).
metastatic melanoma (1 paper, 2020). A melanoma that has spread from its primary site to another anatomic site. "Hypermethylation of GRM6 was detected in renal carcinoma, and LINGO3 was reported as one of the hub genes of metastatic melanoma." (PMID 32701143, 2020).
LINGO3 also shares sentences with these, for which no sentence is quoted: breast carcinoma (1 paper); renal carcinoma (1); tumor (1).